TUBB6 (tubulin beta 6 class V)
Description:
Tubulin is the major constituent of microtubules, a cylinder consisting of laterally associated linear protofilaments composed of alpha- and beta-tubulin heterodimers. Microtubules grow by the addition of GTP-tubulin dimers to the microtubule end, where a stabilizing cap forms. Below the cap, tubulin dimers are in GDP-bound state, owing to GTPase activity of alpha-tubulin.
Synonyms: MGC4083; HsT1601; FPVEPD; TUBB-5
Tractability: Small molecule: an approved drug acts on it; a high-quality ligand is known; it belongs to a druggable protein family. PROTAC: ubiquitination databases record sites on it; its protein half-life has been measured; a small molecule that binds it is known. Other modalities: an approved drug acts on it.
Target class: Structural protein
Gene: Protein-coding gene on chromosome 18 (12,307,287 to 12,344,320, forward strand). Ensembl gene ENSG00000176014.
Subcellular location: Cytoplasm, cytoskeleton
Subcellular location (Human Protein Atlas): Microtubules; Basal body; Cytokinetic bridge; End piece; Flagellar centriole; Mitotic spindle; Primary cilium; Primary cilium tip; Principal piece
Pathways (Reactome):
Cell Cycle: EML4 and NUDC in mitotic spindle formation; Mitotic Prometaphase; Recruitment of NuMA to mitotic centrosomes; Resolution of Sister Chromatid Cohesion; Sealing of the nuclear envelope (NE) by ESCRT-III; Separation of Sister Chromatids; The role of GTSE1 in G2/M progression after G2 checkpoint
Vesicle-mediated transport: COPI-dependent Golgi-to-ER retrograde traffic; COPI-independent Golgi-to-ER retrograde traffic; COPI-mediated anterograde transport; Gap junction assembly; Microtubule-dependent trafficking of connexons from Golgi to the plasma membrane; Translocation of SLC2A4 (GLUT4) to the plasma membrane
Metabolism of proteins: Carboxyterminal post-translational modifications of tubulin; Formation of tubulin folding intermediates by CCT/TriC; Post-chaperonin tubulin folding pathway; Prefoldin mediated transfer of substrate to CCT/TriC
Signal Transduction: Hedgehog 'off' state; RHO GTPases Activate Formins; RHO GTPases activate IQGAPs
Immune System: MHC class II antigen presentation; PKR-mediated signaling
Neuronal System: Activation of AMPK downstream of NMDARs; Assembly and cell surface presentation of NMDA receptors
Organelle biogenesis and maintenance: Cargo trafficking to the periciliary membrane; Intraflagellar transport
Autophagy: Aggrephagy
Cellular responses to stimuli: HSP90 chaperone cycle for steroid hormone receptors (SHR) in the presence of ligand
Developmental Biology: Recycling pathway of L1
Disease: HCMV Early Events
Hemostasis: Kinesins
Gene Ontology:
Molecular function: protein binding; GTP binding; structural constituent of cytoskeleton; GTPase activity
Biological process: mitotic cell cycle; cytoskeleton organization; microtubule-based process
Cellular component: extracellular exosome; microtubule; nucleus; cytoskeleton
Genetic constraint (gnomAD): Loss-of-function variants: 15 observed, 27.97 expected, observed/expected ratio (o/e) 0.54, 90% interval 0.36 to 0.83. The upper end of that interval is the gene's LOEUF score, 0.83, which puts it in group 3 of 6, group 1 being the genes least tolerant of losing a copy. Missense variants: 465 observed, 639.13 expected, observed/expected ratio (o/e) 0.73, 90% interval 0.67 to 0.79. Synonymous variants: 271 observed, 270.11 expected, observed/expected ratio (o/e) 1, 90% interval 0.91 to 1.11.
Homologues: Orthologues: chimpanzee TUBB6 (100% identical), macaque TUBB6 (99% identical), dog TUBB6 (98% identical), rat Tubb6 (98% identical), mouse Tubb6 (97% identical), tropical clawed frog tubb6 (96% identical), zebrafish tubb6 (95% identical), pig TUBB6 (86% identical), guinea pig TUBB6 (59% identical). Paralogues in human: TUBB3 (92% identical), TUBB4A (92% identical), TUBB4B (91% identical), TUBB2B (91% identical), TUBB (91% identical), TUBB2A (91% identical), TUBB8 (85% identical), TUBB8B (83% identical), TUBB1 (78% identical), TUBA1B (43% identical), TUBA4A (42% identical), TUBA1A (42% identical), and 11 more.